GLP1R (glucagon like peptide 1 receptor)
Diseases named in the same sentence as GLP1R in open-access papers (continued):
Sharing a sentence is not in itself a finding about the gene and the disease.
type 2 diabetes (continued). "It has previously been established that both protein and mRNA expression of GLP1R is reduced in islets from patients with type 2 diabetes compared with non-diabetic controls as well as in rodent islets exposed to hyperglycaemia." (PMID 23879380, 2013). "Glucagon-like peptide-1 receptor agonists (GLP-1RAs), such as semaglutide, liraglutide, and exenatide, are an appealing option for the treatment of type 2 diabetes mellitus (T2DM) and obesity." (PMID 40006605, 2025). "This study aimed to evaluate the impact of glucagon-like peptide-1 receptor agonist (GLP-1 RA) plus insulin therapy on long-term cardiovascular and microvascular outcomes in patients with type 2 diabetes (T2D), with the goal of optimizing treatment strategies." (PMID 41011236, 2025). "In the last decade, the management of Type 2 diabetes (T2DM) has evolved significantly with the introduction of novel antidiabetic medications, notably sodium–glucose cotransporter 2 (SGLT2) inhibitors and glucagon-like peptide 1 receptor agonists (GLP-1RAs)." (PMID 41220901, 2025). "Similarly, glucagon-like peptide-1 receptor agonists (GLP-1RAs), initially developed for the treatment of type 2 diabetes, have demonstrated promising cognitive benefits, potentially mediated through improved insulin signaling, neuronal survival, and reduced β-amyloid (Aβ) and tau burden." (PMID 40642529, 2025). "The approved GLP-1R agonists are peptide-based molecules that mimic the action of endogenous GLP-1, enhancing glucose-dependent insulin secretion, suppressing glucagon release, delaying gastric emptying, and thereby improving glycemic control in patients with type 2 diabetes." (PMID 41303737, 2025). "Glucagon-like peptide-1 receptor agonists (GLP-1RAs) and other incretin-based drugs are well-established treatments for type 2 diabetes mellitus (T2DM) and obesity due to their metabolic effects and favorable safety profiles." (PMID 41515925, 2025). "Efpeglenatide, a novel long-acting glucagon-like peptide-1 receptor agonist (GLP-1 RA), shows promise for the treatment of type 2 diabetes mellitus (T2DM) and obesity." (PMID 39917155, 2025). "Background/Objectives: Glucagon-like peptide-1 receptor agonists (GLP-1RAs) have emerged as a transformative therapy for obesity and type 2 diabetes (T2D) in pediatric populations." (PMID 41300545, 2025). "Also, glucagon-like peptide-1 receptor agonists (GLP-1 RAs), beyond their established metabolic effects in type 2 diabetes, may exert protective actions in patients with coexisting COPD." (PMID 40649150, 2025). "Over the past decade, glucagon-like peptide-1 receptor agonists (GLP-1 RAs) have emerged as a transformative class of pharmacotherapies for obesity and type 2 diabetes mellitus (T2D)." (PMID 41465555, 2025). "Furthermore, FWBGI modulates mitochondrial regulation by increasing GLP-1 receptor (GLP-1R) expression and UCP2/3 activity in the liver and brain, suggesting a novel regulatory axis involving the brain, liver, and intestines for managing type 2 diabetes." (PMID 40282189, 2025). "In addition, GLP-1R agonist exendin-4 has been shown to increase antioxidants (SOD-1 and glutathione peroxidase) to improve myocardial oxidative stress and ameliorates cardiac dysfunction in type 2 diabetes." (PMID 40232847, 2025). "Glucagon-like peptide 1 receptor agonists (GLP-1RAs) are approved by the US Food and Drug Administration for treating type 2 diabetes (T2D)." (PMID 38060218, 2024). "Dulaglutide is a long-acting glucagon-like peptide-1 receptor agonist (GLP-1RA), which has been approved for the treatment of patients with type 2 diabetes (T2D)." (PMID 39331877, 2024). "Glucagon-like peptide-1 receptor agonists (GLP-1RAs) are incretin-based agents, used for treatment of type 2 diabetes (T2D) and obesity." (PMID 39633496, 2024).
type 2 diabetes (continued). "Due to their cardiovascular protective effect, glucagon-like peptide-1 receptor agonists (GLP-1RAs) and sodium-glucose cotransporter-2 inhibitors (SGLT2is) represent breakthrough therapies for type 2 diabetes mellitus (T2DM)." (PMID 37005640, 2023). "It is possible that, in subjects without type 2 diabetes, GLP1R blockade may produce greater abnormalities in α cell function in response to fat or protein than to glucose infusion alone." (PMID 37751301, 2023). "Injectable glucagon-like peptide-1 receptor agonist therapies (GLP-1 RAs) are an effective and established modern treatment option for patients with obesity or type 2 diabetes mellitus (T2DM)." (PMID 35526173, 2023). "This cohort study investigates the outcomes of sodium-glucose cotransporter-2 inhibitor (SGLT-2i) and glucagon-like peptide-1 receptor agonist (GLP-1RA) therapy among patients with type 2 diabetes in South Korea, by the presence or absence of nonalcoholic fatty liver disease (NAFLD)." (PMID 38153732, 2023). "The human GLP1R (hmGLP1R) is a prime target for drug screening and drug developmentefforts, since GLP-1 receptor agonists (GLP1RAs) have been used for decades for thetreatment of type 2 diabetes and have more recently become some of the mosteffective and widely used weight-loss drugs." (PMID 37265064, 2023). "Although we were able to ascertain differences in the response to GLP1R blockade between people with and without type 2 diabetes, we may have missed defects in the α cell response to macronutrients other than glucose in people without diabetes." (PMID 37751301, 2023). "The glucagon-like peptide-1 receptor (GLP-1R), a class B G protein–coupled receptor (GPCR), is a prominent target for type 2 diabetes (T2D) and obesity treatment." (PMID 37134170, 2023). "Additionally, the decrease in GLP-1R immunoreactivity in the LH of overweight or obese individuals, shown herein, is comparable to the decreased expression of GLP-1R mRNA reported in the human PVN and IFN of type 2 diabetic patients." (PMID 36499229, 2022). "DMR, when combined with a glucagon-like peptide-1 receptor agonist (GLP-1RA), resulted in discontinuation of exogenous insulin treatment in 69% of patients with insulin dependent type 2 diabetes mellitus (T2DM) in the INSPIRE study." (PMID 36992788, 2022). "Several new classes of drugs used to manage type 2 diabetes have entered the market over the last two decades, including dipeptidyl peptidase-4 inhibitors (DPP-4i), sodium-glucose co-transporter-2 inhibitors (SGLT-2i), and glucagon-like peptide-1 receptor agonists (GLP-1 RAs)." (PMID 36175881, 2022). "Glucagon like peptide-1 receptor agonists (GLP-1RAs) have shown to reduce mortality and cardiovascular events in patients with type 2 diabetes mellitus (T2DM)." (PMID 35397526, 2022). "Glucagon-like peptide-1 receptor (GLP-1R) activation may improve myocardial performance in the context of ischaemia, independent of glycaemic control, in individuals with and without type 2 diabetes mellitus." (PMID 33579317, 2021). "Glucagon-like peptide-1 receptor agonists are becoming the preferred therapeutic option for the management of obesity and are becoming the preferred treatment options for the management of both NAFLD and type 2 diabetes mellitus, but the molecular mechanisms are still unclear." (PMID 33336025, 2020). "Owing to their overall safety and efficacy, glucagon-like peptide-1 receptor agonists (GLP-1RAs) are becoming the preferred therapeutic option for the management of both obesity and type 2 diabetes mellitus (T2DM)." (PMID 33336025, 2020). "How the insulinotropic glucagon-like peptide-1 receptor agonist liraglutide in a physiologic post-prandial setting may act on pancreatic alpha and beta-cell function in patients with coronary artery disease (CAD) and type 2 diabetes (T2DM) is less clear." (PMID 31164926, 2019).
type 2 diabetes (continued). "In patients with type 2 diabetes mellitus (T2DM) and poor glycemic control receiving metformin (MET), glucagon-like peptide-1 receptor agonists (GLP-1 RAs) are recommended as the adjunctive therapy." (PMID 31772945, 2019). "The glucagon-like peptide-1 receptor (GLP-1R), a key pharmacological target in type 2 diabetes (T2D) and obesity, undergoes rapid endocytosis after stimulation by endogenous and therapeutic agonists." (PMID 31430273, 2019). "Moreover, a novel study found that glucagon-like peptide-1 receptor (GLP1R) agonists can block the conversion of trophic to A1 astrocytes, suggesting that Diabetes mellitus type 2 treatments, including liraglutide, may benefit inflammaging and AD." (PMID 30564191, 2018). "In type 2 diabetes mellitus which is characterized by increased non-enzymatic protein glycosylation because of chronic hyperglycemia, GLP-1R agonists might also improve defective glucose transport and glycometabolic control by stimulating AMPK phosphorylation." (PMID 27473212, 2016). "One possibility could be the administration of glucagon-like peptide-1 receptor (GLP-1R) agonists or dipeptidyl peptidase-4 (DPP-4) inhibitors, two incretin-based therapies commonly used for the treatment of type 2 diabetes mellitus due to their effects on body weight reduction." (PMID 26828649, 2016). "Activation of the glucagon-like peptide-1 receptor (GLP-1R) in pancreatic β-cells potentiates insulin production and is a current therapeutic target for the treatment of type 2 diabetes mellitus (T2DM)." (PMID 25180755, 2014). "Such activity may well underlie aspects of the non-insulinotropic anti-diabetic effects of GLP-1R activation that potentially enhance the utility of this system in the treatment of type 2 diabetes." (PMID 23094100, 2012). "It will be important to determine if post-translational modifications such as N-glycosylation are impaired in Type II diabetes, and whether this results in a reduction in cell surface GIPR and GLP-1R number along with the decreased incretin response of the ß-cell." (PMID 22412906, 2012). "The once-weekly (QW) formulation of the glucagon-like peptide-1 receptor agonist exenatide has been demonstrated to improve A1C, fasting plasma glucose (FPG), body weight, serum lipid profiles, and blood pressure in patients with type 2 diabetes through 52 weeks of treatment." (PMID 21529363, 2011). "The development of orally bioavailable non-peptidomimetic glucagon-like peptide-1 receptor agonists (GLP-1RAs) offers a promising therapeutic avenue for the treatment of type 2 diabetes mellitus (T2DM) and obesity." (PMID 40649923, 2025). "The so-called incretin effect is significantly diminished or nonexistent in patients with type 2 diabetes (T2DM) compared to healthy participants, which makes the GLP-1 receptor (GLP-1R) a desirable target for antidiabetic management with GLP-1RAs." (PMID 40872522, 2025). "Glucagon-like peptide-1 receptor agonists (GLP-1RA) are increasingly used in adults with type 2 diabetes (T2D), with or without obesity." (PMID 40917760, 2025). "Glucagon-like peptide-1 receptor agonists (GLP-1RAs) are a class of drugs that have been gaining more attention in recent years for their efficacy and safety in treating type 2 diabetes mellitus (T2DM)." (PMID 38515845, 2024). "For women of reproductive years living with type 2 diabetes, the relative merits of using non-insulin pharmacotherapies vs diabetes technology (dipeptidyl peptidase-4 inhibitors, glucagon-like peptide-1 receptor agonists and sodium−glucose cotransporter 2 inhibitors) are unknown." (PMID 38967667, 2024). "Models were applied to an illustrative example in type 2 diabetes; using data from a systematic review of RCTs and non-randomised studies of two classes of glucose-lowering medications: sodium-glucose co-transporter 2 inhibitors and glucagon-like peptide-1 receptor agonists." (PMID 37087450, 2023).
type 2 diabetes (continued). "Glucagon-like peptide-1 receptor agonists (GLP-1RA) have a more potent glycated hemoglobin (HbA1c)-lowering effect than existing therapies and are widely used for treating type 2 diabetes mellitus (T2DM)." (PMID 37103055, 2023). "Semaglutide, a glucagon-like peptide-1 receptor agonist (GLP-1RA), was developed as an antihyperglycemic agent and has been shown to improve multiple health outcomes for patients with type 2 diabetes mellitus (T2DM)." (PMID 38028337, 2023). "Glucagon-like peptide-1 (GLP-1) receptor (GLP-1R) agonists have been approved for the treatment of type 2 diabetes mellitus (T2DM); however, the brain actions of these drugs are not properly established." (PMID 36555587, 2022). "For example, randomisation to the glucagon-like peptide-1 receptor agonist (GLP1RA) semaglutide 2.4 mg once weekly plus lifestyle intervention resulted in 10-15% weight loss by follow-up at week 68 in patients with overweight or obesity, with or without type 2 diabetes." (PMID 36259366, 2022). "Glucagon like peptide-1 receptor agonist (GLP1RA) based therapies have been in use since 2005 and GLP1RAs have been extensively studied for the treatment of type 2 diabetes mellitus (T2DM)." (PMID 32571416, 2020). "Recent renal outcome trails with agents such as thiazolidinediones, DPP-4 inhibitors, bardoxolone, and sulodexide have been unsuccessful; however, exciting new data from trials with GLP1R agonists and SGLT2 inhibitors show beneficial renal effects in patients with type 2 diabetes mellitus (T2DM)." (PMID 29629372, 2018). "This study demonstrates experimentally that pre-stroke pharmacological targeting of obesity by GLP-1R and NPY2R activation in type 2 diabetes enhances stroke recovery, without effects additional to weight loss mediated by the treatments." (PMID 41094027, 2026). "Glucagon-like peptide-1 receptor agonists (GLP-1 RAs) significantly reduce major adverse cardiovascular events in patients with and without Type 2 diabetes, offering benefits that extend beyond glycemic control." (PMID 42130151, 2026). "Class B GPCRs, such as the glucagon-like peptide-1 receptor (GLP-1R), play crucial roles in the control of glucose and energy metabolism and are key investigational targets for the treatment of several metabolic disorders including insulin resistance, obesity, and type 2 diabetes (T2D)." (PMID 31430273, 2019). "As a consequence, long-acting, DPP-4 resistant GLP-1R agonists, but not GIP-R agonists, have been developed and clinically approved for the treatment of type 2 diabetes." (PMID 29641447, 2018). "The presented findings that GLP-1 receptor is abundant in the magnocellular subdivision of the PVN (PVNmc) and is overexpressed in type 2 diabetes mellitus (T2DM) suggest that GLP-1R in the PVNmc may have special role in the dysregulation of feeding behaviour and glucose homeostasis in T2DM." (PMID 36555587, 2022). "Glucose-insulinotropic peptide (GIP) incretin could be also another alternative in type-2 diabetes treatment, especially as the GIP receptor (GIP-R) was not expressed in the normal thyroid and the exocrine pancreas unlike GLP-1R." (PMID 23641235, 2013). "This may suggest that increased islet GLP1R protein levels, if existent also in humans with IGT or type 2 diabetes, may not be sufficient to counteract the β-cell dysfunction in these subjects." (PMID 23781322, 2013). "Sodium-glucose co-transporter 2 (SGLT2) inhibitors, glucagon-like peptide-1 receptor (GLP-1R) agonists, and dipeptidyl peptidase 4 (DPP-4) inhibitors showed significant benefit on cardiovascular outcomes in both patients with and without type 2 diabetes mellitus (DM)." (PMID 33843015, 2022). "Prospective evaluation of dual therapy with GLP-1R agonists and SGLT2 inhibitors on cardiovascular outcomes is of great interest to assess if a synergistic effect exists with multimodal inhibition of pathological pathways in patients with and without type 2 diabetes." (PMID 36561085, 2022).
diabetes (1,426 papers, 2005 to 2026). "We determined experimentally that pre-stroke weight loss by GLP-1R/NPY2R activation strongly improves stroke recovery in diabetes." (PMID 41094027, 2026). "A clear limitation of this study is that it is unlikely that a GIPR agonist or antagonist will be given alone for the treatment of obesity/diabetes as weight loss is modest compared to GLP‐1R agonism." (PMID 41287212, 2026). "One promising class of drugs that has gained attention for their efficacy in promoting weight loss and managing diabetes is Glucagon-like peptide 1 receptor agonists (GLP-1 RAs)." (PMID 40890660, 2025). "There has been a rapid increase in the use of glucagon-like peptide-1 receptor agonists (GLP-1 RA) in managing diabetes and weight loss." (PMID 40150111, 2025). "For example, semaglutide, a glucagon-like peptide-1 receptor (GLP-1R) agonist, has demonstrated reliable weight loss effects in treating obesity and diabetes." (PMID 39974186, 2025). "Meanwhile, LB-A has also demonstrated the potential to alleviate chronic inflammation associated with diabetes and to upregulate GLP-1R in mice." (PMID 41373699, 2025). "GLP-1 agonists (GLP-1s), including semaglutide, liraglutide, dulaglutide, and tirzepatide, are exogenous incretin mimetics that can bind to GLP-1R independently of food intake, effectively managing diabetes and promoting weight loss in obesity." (PMID 40361517, 2025). "Glucagon-like peptide 1 receptor agonist (GLP-1RA) incretin therapies are now used by over 12% of US adults for diabetes and weight loss." (PMID 41312422, 2025). "This review addresses the growing concern of oral side effects, particularly dry mouth, associated with semaglutide, a glucagon-like peptide-1 receptor agonist (GLP-1RA) widely used for diabetes and obesity." (PMID 41463424, 2025). "Glucagon-like peptide-1 receptor agonists, semaglutide, obesity, diabetes and cardiovascular risk were incorporated into the electronic databases for the search strategy." (PMID 38786967, 2024). "Glucagon-like peptide-1 receptor agonists (GLP-1 RA) are frequently used for diabetes and weight loss management." (PMID 39640084, 2024). "We demonstrated that higher genetic GLP1R expression was consistently associated with reduced kidney disease progression after adjusting for BMI and diabetes status." (PMID 39453656, 2024). "GLP-1R agonists have hence been examined as a potential therapy for diabetes, neurodegeneration and vision loss in Wolfram syndrome." (PMID 36995380, 2023). "Previous studies have shown that GLP1R polymorphisms are associated with susceptibility to diabetes and clinical responsiveness to different hypoglycemic agents." (PMID 38131033, 2023). "Previous studies have reported that GLP1R gene polymorphisms are closely related to insulin secretion and response to GLP1R analogs in diabetes patients." (PMID 38131033, 2023). "OA and 5% ethanol alone or in combination suppresses the blood glucose level of β-cell deficiency induced diabetes by increasing islet GLP-1R expression." (PMID 37520251, 2023). "One pharmacologic intervention with potential to address diabetes mellitus, obesity and associated cardiometabolic conditions in patients with obstructive sleep apnea is glucagon-like peptide-1 receptor agonists (GLP-1RAs)." (PMID 36013401, 2022). "It is reasonable to assume that even with GCGR mutations in β cells, glucagon binding to GLP-1R exerts an insulin-promoting effect that can reduce blood glucose concentrations in patients with diabetes." (PMID 35784565, 2022). "Glucagon-like peptide-1 receptor agonists (GLP-1 RAs) originally emerged as drugs for the management of diabetes, but have also been shown to alleviate cardiorenal risk." (PMID 36230573, 2022). "In 2020, the American Diabetes Association suggested that SGLT2is are preferred over glucagon-like peptide 1 receptor agonists as a second-line option added to metformin for patients with diabetes with HF history." (PMID 36294837, 2022).